YAP1 (Yes1 associated transcriptional regulator)
Diseases named in the same sentence as YAP1 in open-access papers (continued):
Sharing a sentence is not in itself a finding about the gene and the disease.
esophageal cancer (continued). "The increase in YAP1 activity can induce EGFR expression in esophageal cancer cells, thus conferring resistance to 5-fluorouracil and docetaxel." (PMID 36045416, 2022). "The observed anti-tumor function of YAP1 was further supported by a better overall survival among esophageal cancer patients with a high YAP1 expression." (PMID 35930163, 2022). "We found that YAP1 functions as a tumor suppressor whereas TAZ exerts pro-tumor functions in esophageal cancer cells." (PMID 35930163, 2022). "Collectively, we found that YAP1 and TAZ have opposing functions and that YAP1 negatively regulates TAZ expression in esophageal cancer." (PMID 35930163, 2022). "We also examined the impact of YAP1 or TAZ deregulation on clinical outcome of esophageal cancer patients from the TCGA database." (PMID 35930163, 2022). "In esophageal cancer, YAP1 was shown to confer cancer stem cell properties by activating SOX9 via TEAD-mediated binding." (PMID 36045416, 2022). "Our finding is, however, contradictory to the oncogenic function of YAP1 previously reported in esophageal cancer." (PMID 35930163, 2022). "In this report, we focused on the interplay of YAP1 and TAZ and the mechanism underlying in esophageal cancer." (PMID 35930163, 2022). "Under the condition of YAP1 depletion in esophageal cancer cells and xenograft tumorigenesis, we also detected an increase in TAZ expression." (PMID 35930163, 2022). "We found that the expression level of YAP mRNA was at least four times higher than that of TAZ in the esophageal cancer lines, indicating a dominant role of YAP1 in these cells." (PMID 35930163, 2022). "In contrast to the promoting effect of YAP1 silencing on esophageal cancer cells, TAZ knockdown reproducibly reduced esophageal cancer cell proliferation, migration and invasion in both lines when compared to shLuc control cells." (PMID 35930163, 2022). "In contrast to the reported oncogenic actions of YAP1 overexpression in several cancer types, our depletion and ectopic expression studies support a suppressive function of YAP1 expression on esophageal cancer cell proliferation, migration and invasion." (PMID 35930163, 2022). "FAT1 promotes the expression of PTPN14 and downregulates the expressions of Yap1 and Myc, to inhibit the proliferation, adhesion, and invasion of human esophageal cancer cell lines." (PMID 34712552, 2021). "Our results showed that FAT1 and PTPN14 are downregulated while Yap1 is upregulated in esophageal cancer tissues." (PMID 34712552, 2021). "Results showed that FAT1 and PTPN14 were downregulated, while Yap1 was upregulated in esophageal cancer tissues." (PMID 34712552, 2021). "Recently, it was observed that YAP1 mediates an increase of GLUT1 in esophageal cancer to promote resistance to therapy." (PMID 34307352, 2021). "The results showed that Yap1 mRNA was highly expressed in esophageal carcinoma tissues, but low in the adjacent tissues of esophageal carcinoma." (PMID 34712552, 2021). "BART results for up-regulated genes in stomach and esophageal carcinoma (STES) rank YAP1 and TEAD4 among the top three ranked putative TRs." (PMID 33778495, 2021). "This is supported by a 2016 study that has shown YAP1 knockdown suppresses esophageal carcinoma and proposes YAP1 to be a target for gene therapy." (PMID 33778495, 2021). "The expression of Yap1 was low in the adjacent tissues of esophageal carcinoma, but high in the tissues of esophageal carcinoma." (PMID 34712552, 2021). "Induction of YAP1 expression in esophageal cancer cells up-regulated CDK6 expression, increased transcription, and consequently induced the resistance against radiotherapy." (PMID 33665161, 2020). "For example, it was reported that exogenous induction of YAP1 induced esophageal cancer cell resistance to 5FU and docetaxel." (PMID 31543507, 2019). "YAP1 upregulates also EGFR expression is esophageal cancer cells, acting at the transcription level through binding to the EGFR promoter." (PMID 28930282, 2017).
esophageal cancer (continued). "In esophageal cancer, YAP1 induces EGFR expression by binding to the TEAD binding site in the EGFR promoter." (PMID 29228705, 2017). "Our findings here strengthen previous reports that Yap1 endows esophageal cancer cells with stem-like properties and link tumor progression with lung tumor propagating cells (TPCs)." (PMID 26695440, 2016). "Yap1 was also reported to be a new regulator of TICs or stem-like cancer cells in lung tumor and esophageal cancer." (PMID 26695440, 2016). "In lung and esophageal cancers Sox9 is activated by Notch pathway and in the esophagus, Sox9 is also a YAP1 target." (PMID 27105493, 2016). "Up regulation and increased nuclear localization of Hippo pathway transcription factor YAP1 was reported to be the independent marker for worse survival of esophageal cancer." (PMID 24621512, 2014). "It has been shown that esophageal cancer patients with upregulation of YAP1 had a worse overall survival than those with normal expression of YAP1." (PMID 24621512, 2014). "Using immunohistochemistry analysis we observed upregulation of YAP1 in a significant portion of esophageal cancer samples." (PMID 24621512, 2014). "We conducted immunohistochemistry experiment to analyze the expression level of YAP1 in the esophageal cancer samples, and found that the cancer patients with smoking history showed high expression of YAP1 compared with the non-smoking patients (P<0.05)." (PMID 24621512, 2014). "We investigated the subcellular localization of YAP1 in esophageal cancer KYSE510 cell using confocal immunofluorescence microscope following exposure to Nicotine." (PMID 24621512, 2014). "Moreover, analysis of data from the GEPIA database revealed a significant correlation between Ezrin and YAP1 levels in esophageal cancer tissue (P = 0.0024; R = 0.1)." (PMID 37791063, 2023). "A strong association of high YAP1 mRNA expression with better overall survival among esophageal cancer patients further supports a negative role of YAP1 in esophageal cancer development." (PMID 35930163, 2022). "YAP1 may function as either a tumor suppressor or promoter and was found to be predominantly expressed in esophageal cancer cells." (PMID 35930163, 2022). "Whether YAP1 mediates the suppression of TAZ translation also via RNA modification in esophageal cancer cells remains to be established." (PMID 35930163, 2022). "We found a higher YAP1 expression than TAZ expression in several esophageal cancer cell lines." (PMID 35930163, 2022). "However, YAP1 overexpression in esophageal cancer has a longer median survival time, contrary to some previous research results and our meta-analysis results." (PMID 35911146, 2022). "The lack of clinical impact of high TAZ expression may be attributed to a much lower level of TAZ expression than that of YAP1 in esophageal cancer cells." (PMID 35930163, 2022). "The role of TAZ has been least explored compared to YAP1 in esophageal cancer." (PMID 35930163, 2022). "FAT1 inhibited the proliferation, adhesion, and invasion of human esophageal cancer cell lines, which might be associated with the upregulation of PTPN14 and the inhibition of Yap1 and Myc." (PMID 34712552, 2021). "Together, these data showed that FAT1 inhibited the cell proliferation, adhesion, and invasion of human esophageal cancer, which might be associated with the upregulation of PTPN14 and inhibition of Yap1 and Myc." (PMID 34712552, 2021). "However, high levels of YAP1 expression were observed to be a favorable indicator for ESCA (Esophageal carcinoma) patients (n = 182, Log-rank p = 0.012, HR = 0.56)." (PMID 34257617, 2021). "A similar YAP1 upregulation of EGFR overexpression confers chemoresistance in esophageal cancer." (PMID 29435131, 2018). "Moreover, verteporfin, a YAP1 inhibitor, promotes sensitivity to 5-fluorouracil and docetaxel by directly inhibiting YAP1 and endothelial growth factor receptor in esophageal cancer cells." (PMID 27206784, 2016).
esophageal cancer (continued). "Furthermore, consistent with a recent study in esophageal cancer, verteporfin diminished both total and phospho-YAP1 levels and EGFR expression, both alone and in combination with cisplatin or erlotinib or radiation treatment." (PMID 26716514, 2016). "Thus we used clinical esophageal cancer samples to examine the correlation between upregulated expression of YAP1 and cigarette smoking." (PMID 24621512, 2014). "Thus we discovered a novel link between cigarette smoking and the oncogenic activity of YAP1 in esophageal cancer." (PMID 24621512, 2014). "Moreover, YAP1 was reported to be upregulated in esophageal cancers and is determined as an oncogene in esophageal cancer." (PMID 24621512, 2014). "However, we did not observe a significant difference in the overall survivals between YAP1-high and YAP1-low groups, probably due to these cancer samples were from T3 stage esophageal cancers patients." (PMID 24621512, 2014). "Importantly, we found a significant association between YAP1 upregulation and cigarette smoking, indicating a causal relationship between cigarette smoking and the oncogenic activation of YAP1 in esophageal cancer." (PMID 24621512, 2014). "Upregulation and increased nuclear translocation of YAP1 have been reported in esophageal cancers." (PMID 24621512, 2014). "Thus we attempted to explore the possible connection between nicotine exposure and YAP1 activation in esophageal cancer in this study." (PMID 24621512, 2014). "Together, YAP1 could regulate TAZ expression via translation control in esophageal cancer cells." (PMID 35930163, 2022). "Thus, in the acquisition of CSC propertiesYAP1 driven SOX9 expression is critical, indicating that YAP1 inhibition might be an attractive option in targeting CSC population in esophageal cancer." (PMID 33665161, 2020). "Thus, targeting YAP1 may provide a novel therapeutic strategy for tumors with high YAP1 expression in esophageal cancer (EC)." (PMID 32175692, 2020). "Importantly, YAP1 inhibitors sensitize esophageal cancer cells to cytotoxic agents and may offer a strategy to bypass chemoresistance in these cells." (PMID 28930282, 2017). "Together, these findings suggest that the nicotine activated nAChRs signaling pathway which further activates YAP1 plays an important role in the development of esophageal cancer, and this mechanism may be of a general significance for the carcinogenesis of smoking related cancers." (PMID 24621512, 2014). "After they treated the resistant esophageal cancer cells with the YAP1 inhibitor CA3, they found that the resistant esophageal cancer cells regained their sensitivity to radiation." (PMID 40723817, 2025). "The novel YAP1 inhibitor, CA3, has demonstrated significant efficacy in reducing tumor sphere formation, inducing apoptosis, and inhibiting proliferation in esophageal cancer cells." (PMID 37215986, 2023). "From our data we conclude that YAP1 functions as a suppressor and negatively regulates pro-tumor TAZ expression via transcriptional and translational control in esophageal cancer." (PMID 35930163, 2022). "The exact role of YAP1 and TAZ in esophageal cancer, the 6th leading cancer-related mortality in the world, remains elusive." (PMID 35930163, 2022). "Another YAP1 inhibitor, verteporfin, targeted the YAP1/TEAD complex and inhibited cancer stemness and cell growth in esophageal cancer and PC." (PMID 36180487, 2022). "Bioinformatics analysis was used to analyze OTUB2 expression in esophageal carcinoma and interactions between OTUB2 and YAP1/TAZ." (PMID 35850645, 2022). "In this study, we examined the expression levels of Yap1, PTPN14, and FAT1 in human esophageal cancer cell lines and tissues." (PMID 34712552, 2021). "By blocking YAP1 and CDK6 with the YAP1 inhibitor CA3, and the CDK6 inhibitor LEE001 significantly suppressed esophageal cancer cell growth and CSC properties, particularly in radiation-resistant cells in both OAC and OSCC." (PMID 33665161, 2020).
esophageal cancer (continued). "Consistently, we observed nuclear translocation and activation of YAP1 by knockdown of CHRNA3, which is a negative regulator of nicotine signaling in bronchial and esophageal cancer cells." (PMID 24621512, 2014). "These clinical data, together with the cell-based assays and xenograft tumorigenesis, support a negative role of YAP1 expression in esophageal cancer development." (PMID 35930163, 2022). "Since we also detected an increase in TAZ mRNA expression in YAP1-depleted grafted tumors and one esophageal cancer line, we cannot completely rule out transcriptional regulation of TAZ expression upon YAP1 depletion." (PMID 35930163, 2022). "To confirm the negative role of YAP1 expression in esophageal cancer cells, we performed lentiviral transduction for ectopic expression of Flag-tagged YAP1-2α in relatively low YAP1 expressing KYSE-70 cells followed by various functional assays." (PMID 35930163, 2022). "Besides, immunohistochemistry was conducted on the same samples of esophageal cancer to analyze the relative protein expression of FAT1 and Yap1." (PMID 34712552, 2021). "Additionally, YAP1 upregulates EGFR expression and increases cell proliferation and therapy resistance in esophageal cancer." (PMID 31601234, 2019). "Upstream of SOX9, YAP1 has been shown to be a major determinant of cancer stem cell properties in non-transformed and esophageal cancer cells." (PMID 26447543, 2015). "In the immunohistochemical analysis we examined 83 T3 stage esophageal cancer samples including 29 non-smokers and 54 smokers, among which we found 49 cancer samples with median or strong upregulation of YAP1 (60%)." (PMID 24621512, 2014). "To investigate whether the mRNA expression of YAP1 or TAZ was deregulated in primary esophageal cancer specimens, we performed an in silico analysis using publicly available gene expression datasets for esophageal cancer from The Cancer Genome Atlas (TCGA)." (PMID 35930163, 2022). "In general, high YAP1 expression was risky in adrenocortical carcinoma (ACC), BLCA, COAD, brain lower grade glioma (LGG), LUAD, and pancreatic adenocarcinoma (PAAD), but it is a protective factor in esophageal carcinoma (ESCA), KIRC, PRAD, and mesothelioma (MESO)." (PMID 36479120, 2022). "So, considering that there may be treatment differences affecting the analysis results, we excluded patients receiving chemoradiotherapy from analysis and found that there was no statistical difference between the YAP1 expression and prognosis in esophageal cancer." (PMID 35911146, 2022). "Further analysis of the TCGA data by Gene Expression Profiling Interactive Analysis 2 (GEPIA2) showed increased expression of YAP1 and TAZ in esophageal cancer tissues relative to normal tissues without reaching statistical significance." (PMID 35930163, 2022). "Our previous study demonstrated that YAP1 confers CSCs properties to nontumorigenic cells and cancer cells by regulating SOX9 in esophageal cancer." (PMID 31601234, 2019). "Yap1 directly upregulated SOX9, and served as a primary determinant of TIC properties in non-transformed cells and in esophageal cancer cells." (PMID 26695440, 2016).
lung adenocarcinoma (48 papers, 2014 to 2025). A carcinoma that arises from the lung and is characterized by the presence of malignant glandular epithelial cells. "Previous studies have demonstrated that the increased expression of YAP1 or its analog TAZ significantly diminishes the sensitivity of the lung adenocarcinoma cell line carrying the BRAF V600E mutation (HCC364) to vemurafenib and trametinib." (PMID 38499647, 2024). "It is shown that miR-630 expression levels are related to gefitinib resistance via miR-630/YAP1/ERK feedback loop in EGFR-mutated lung adenocarcinoma cells." (PMID 37697308, 2023). "Based on the log‐rank test and TCGA database, high mRNA expression of YAP1 was also significantly associated with poor overall survival in patients with lung adenocarcinoma [n =576, HR, 1.54; 95% CI: 1.17–2.03; p‐value = 0.002]." (PMID 33486901, 2021). "To identify if YAP1 is a possible target for EGFR-dependent lung adenocarcinomas, we investigated the correlation between EGFR mutation status and YAP1 expression in 164 cases of NSCLC tissue." (PMID 29163769, 2017). "Recently, we identified the YAP1 R331W missense mutation as an allele that predisposes to lung adenocarcinoma in Taiwan with high familial penetrance." (PMID 27449093, 2016). "Recently, we further identified the YAP1 R331W missense mutation as an allele predisposing to lung adenocarcinoma in Taiwan with high familial penetrance." (PMID 27449093, 2016). "Our analysis of human tumor data showed that over 75% of RIT1-altered lung adenocarcinomas harbor co-occurring loss of expression of at least one Hippo pathway gene, and we verified high rates of YAP1 nuclear staining in an independent RIT1-mutant tumor cohort." (PMID 34373451, 2021). "This profile mirrors that of YAP1 expression in lung adenocarcinoma vs. small-cell lung cancer (SCLC)." (PMID 38968122, 2024). "Subsequent investigations demonstrated that inhibiting YAP1 genetically or pharmacologically suppressed tumor growth in ALK-TKI-resistant lung adenocarcinoma cells, EML4-ALK transgenic mice, and tumor xenograft models." (PMID 38499647, 2024). "This profile mirrors that of YAP1 expression in lung adenocarcinoma versus small cell lung cancer (SCLC)." (PMID 38645034, 2024). "To investigate the role of LINC01117 in regulating the Hippo pathway in lung adenocarcinoma cells, we extracted total protein, cytoplasmic and nuclear proteins and assayed YAP1 levels in A549 cells with LINC01117 overexpression and knockdown." (PMID 37384755, 2023). "This correlation is corroborated by another study demonstrating increased YAP1 amplification frequencies in a cohort of lung adenocarcinoma patients with brain metastasis." (PMID 38067201, 2023). "In this regard, YAP1 amplification was reported to occur at a higher frequency in lung adenocarcinoma brain metastases compared to primary tumors." (PMID 37835395, 2023). "The results showed that there was a significantly higher interaction of YAP1 and HIF1α in lung adenocarcinomas as well as lung squamous cell carcinomas compared with normal tissues." (PMID 35937460, 2022). "COPB2 was reported to promote cell proliferation and tumorigenesis through up-regulating YAP1 expression in lung adenocarcinoma cells." (PMID 35715770, 2022). "In mouse lung adenocarcinoma cells, YAP1 was able to rescue KRAS depleted cells, suggesting a relevant mechanism to bypass loss of KRAS signaling." (PMID 32576853, 2020). "The expression of YAP1 modestly but positively correlated with DGUOK in the lung adenocarcinoma tissue microarray (Spearman's rank rs = 0.369, P < 0.0001)." (PMID 31633874, 2019). "The decreases in YAP1 protein levels were also observed in DGUOK KO lung adenocarcinoma PDCs (Fig EV4B)." (PMID 31633874, 2019). "Our studies in bladder cancer and lung adenocarcinoma have demonstrated a crucial role of YAP1, a transcriptional regulator of genes that promote cell survival and proliferation, in regulating CSC phenotypes." (PMID 31137841, 2019).